FAM227A (family with sequence similarity 227 member A)
Tractability: No criterion of Open Targets' tractability assessment is met for any kind of drug.
Gene: Protein-coding gene on chromosome 22 (38,578,118 to 38,656,629, reverse strand). Ensembl gene ENSG00000184949.
Subcellular location (Human Protein Atlas): Nucleoplasm
Genetic constraint (gnomAD): Loss-of-function variants: 44 observed, 47.05 expected, observed/expected ratio (o/e) 0.94, 90% interval 0.73 to 1.2. The upper end of that interval is the gene's LOEUF score, 1.2, which puts it in group 5 of 6, group 1 being the genes least tolerant of losing a copy. Missense variants: 528 observed, 572.03 expected, observed/expected ratio (o/e) 0.92, 90% interval 0.86 to 0.99. Synonymous variants: 184 observed, 210.51 expected, observed/expected ratio (o/e) 0.87, 90% interval 0.77 to 0.99.
Homologues: Orthologues: chimpanzee FAM227A (94% identical), macaque FAM227A (89% identical), pig FAM227A (64% identical), dog FAM227A (59% identical), rabbit FAM227A (55% identical), mouse Fam227a (52% identical), rat Fam227a (51% identical).
Diseases named in the same sentence as FAM227A in open-access papers:
FAM227A is named in the same sentence as 6 diseases in open-access papers, as found by Europe PMC text mining. Sharing a sentence is not in itself a finding about the gene and the disease. The quoted sentences say what the papers report.
cholesteatoma (1 paper, 2022). A pathologic process characterized by the proliferation of keratinizing squamous epithelium resulting in the accumulation of keratin and cells in the middle ear and/or mastoid. "However, in our own middle ear expression dataset from the same patients, all 12 genes were DEGs for cholesteatoma: RTN4, RAB5A, CRYBG1, RGS22, HEPHL1, and SPTLC3 were upregulated, while APBB1IP, BHLHE41, ARID3A, C5AR1, CPT1B, and FAM227A were downregulated." (PMID 36699445, 2022).
co-infection (1 paper, 2025). "Regarding the co-infection of cells by E. coli and S. aureus, the unique genes of ES2 are DZIP1 and SMTNL2; the unique genes of ES3 are ALDH4A1, DNASE1L1, FAM227A, and KAT2B; and ES1 has 143 unique genes." (PMID 40771952, 2025).
prostate carcinoma (1 paper, 2024). A carcinoma that arises from epithelial cells of the prostate gland. "One genome scan study showed that the deletion region of chromosome 22q13, where FAM227A is located, might be associated with the risk of aggressive prostate cancer." (PMID 38410974, 2024). "We further observed an increased expression of FAM227A in prostate cancer tissues, compared with normal tissues in the GSE200879 dataset." (PMID 38410974, 2024). "Compared with that in normal tissues, the FAM227A expression was upregulated in prostate cancer tissues." (PMID 38410974, 2024). "Notably, FAM227A expression was higher in CRPC tissues than in hormone-naive prostate cancer tissues in GSE200879." (PMID 38410974, 2024). "The evidence provided by the current study indicates that FAM227A may be a prostate cancer inducer." (PMID 38410974, 2024). "Thus, FAM227A might participate in the pathogenesis and development of prostate cancer by regulating these known pathways." (PMID 38410974, 2024). "Finally, to investigate potential molecules contributing to prostate cancer, we performed Gene Set Enrichment Analysis (GSEA) based on the differentially expressed genes between the FAM227A high- and low-expression cancer tissues." (PMID 38410974, 2024).
cancer (1 paper, 2024). A tumor composed of atypical neoplastic, often pleomorphic cells that invade other tissues. "The expression of FAM227A was significantly higher (stratified by Gleason score, pathologic T stage, pathologic N stage, and biochemical recurrence status) in cancer subgroups than in normal tissue subgroup (Pall < 0.05)." (PMID 38410974, 2024).
FAM227A also shares sentences with these, for which no sentence is quoted: otitis media (1 paper); tumor (1).